RNU6-1297P (RNA, U6 small nuclear 1297, pseudogene)
Gene: Small nuclear RNA gene on chromosome 1 (155,419,397 to 155,419,500, forward strand). Ensembl gene ENSG00000207144.
Homologues: Orthologues: chimpanzee U6 (100% identical), macaque U6 (95% identical), pig U6 (79% identical). Paralogues in human: RNU6-1029P (89% identical), RNU6-1011P (88% identical), RNU6-1124P (88% identical), RNU6-39P (88% identical), RNU6-842P (88% identical), RNU6-1117P (88% identical), RNU6-12P (88% identical), RNU6-13P (88% identical), RNU6-140P (88% identical), RNU6-16P (88% identical), RNU6-25P (88% identical), RNU6-29P (88% identical), and 1291 more.